BAG5 (BAG cochaperone 5)
Description:
Co-chaperone for HSP/HSP70 proteins. It functions as a nucleotide-exchange factor promoting the release of ADP from HSP70, thereby activating HSP70-mediated protein refolding. Has an essential role in maintaining proteostasis at junctional membrane complexes (JMC), where it may function as a scaffold between the HSPA8 chaperone and JMC proteins enabling correct, HSPA8-dependent JMC protein folding (By similarity). Inhibits both auto-ubiquitination of PRKN and ubiquitination of target proteins by PRKN (By similarity).
Synonyms: BAG-5; CMD2F
Tractability: PROTAC: ubiquitination databases record sites on it; its protein half-life has been measured.
Gene: Protein-coding gene on chromosome 14 (103,556,545 to 103,562,657, reverse strand). Ensembl gene ENSG00000166170.
Subcellular location (Human Protein Atlas): Vesicles; Basal body; Centrosome; Nucleoplasm; Plasma membrane; Primary cilium; Primary cilium tip
Pathways (Reactome):
Cellular responses to stimuli: Regulation of HSF1-mediated heat shock response
Gene Ontology:
Molecular function: protein binding; protein kinase binding; protein-folding chaperone binding; ubiquitin protein ligase binding; adenyl-nucleotide exchange factor activity; ubiquitin ligase inhibitor activity
Biological process: Golgi organization; negative regulation of neuron projection development; negative regulation of oxidative stress-induced intrinsic apoptotic signaling pathway; negative regulation of proteasomal ubiquitin-dependent protein catabolic process; negative regulation of protein ubiquitination; protein stabilization; regulation of inclusion body assembly; negative regulation of protein refolding; protein folding
Cellular component: cytosol; inclusion body; membrane; mitochondrion; nucleus; perinuclear region of cytoplasm; junctional membrane complex; cytoplasm
Genetic constraint (gnomAD): Loss-of-function variants: 25 observed, 33.57 expected, observed/expected ratio (o/e) 0.74, 90% interval 0.54 to 1.04. The upper end of that interval is the gene's LOEUF score, 1.04, which puts it in group 4 of 6, group 1 being the genes least tolerant of losing a copy. Missense variants: 491 observed, 557.83 expected, observed/expected ratio (o/e) 0.88, 90% interval 0.82 to 0.95. Synonymous variants: 208 observed, 218.32 expected, observed/expected ratio (o/e) 0.95, 90% interval 0.85 to 1.07.
Gene-disease validity (ClinGen):
ClinGen rates the evidence that BAG5 causes each of these diseases.
cardiomyopathy, dilated, 2F (autosomal recessive): Moderate. A dilated cardiomyopathy that is characterized by refractory ventricular arrhythmias and severe heart failure and that has material basis in homozygous mutation in the BAG5 gene on chromosome 14q32.
Homologues: Orthologues: chimpanzee BAG5 (99% identical), macaque BAG5 (99% identical), dog BAG5 (96% identical), mouse Bag5 (91% identical), guinea pig BAG5 (91% identical), rat Bag5 (91% identical), pig BAG5 (88% identical), tropical clawed frog bag5 (66% identical), zebrafish bag5 (53% identical), Drosophila melanogaster stv (10% identical). Paralogues in human: BAG3 (18% identical), BAG4 (12% identical).
Diseases named in the same sentence as BAG5 in open-access papers:
BAG5 is named in the same sentence as 48 diseases in open-access papers, as found by Europe PMC text mining. Sharing a sentence is not in itself a finding about the gene and the disease. The quoted sentences say what the papers report.
Parkinson disease (8 papers, 2014 to 2024). A progressive degenerative disorder of the central nervous system characterized by loss of dopamine producing neurons in the substantia nigra and the presence of Lewy bodies in the substantia nigra and locus coeruleus. "This suggests that BAG5 is involved in proteasome-mediated protein degradation, which is also associated with Parkinson’s disease." (PMID 35968372, 2022). "BAG5 is also implicated in selective autophagy through its interaction with P62 in the context of Parkinson’s disease (PD)." (PMID 35203329, 2022). "This study suggests that BAG5 also involves in proteosome-mediated protein degradation, which is associated with Parkinson's disease." (PMID 24475098, 2014). "Bcl-2 associated athanogene 5 (BAG5) is a co-chaperone that modulates proteostasis by inhibiting the activity of Heat shock protein 70 (Hsp70) and several E3 ubiquitin ligases, resulting in enhanced neurodegeneration in models of Parkinson’s disease (PD)." (PMID 32850835, 2020). "This review will discuss the evolving role of co-chaperone Bcl-2 associated anthanogene protein (BAG5) in UPS, autophagy, mitophagy, oxidative stress, metabolism, and its association with CVDs, Alzheimer’s disease, and Parkinson’s disease." (PMID 35821856, 2022). "BAG5 has been reported to take part in the development of neurodegenerative diseases, including the Alzheimer’s disease and Parkinson disease, through unclear mechanism." (PMID 27807478, 2016). "The characterization of the interaction between PINK1 and BAG5 under physiological status or pathological state will lead to an improved understanding of the pathogenesis of Parkinson's disease and, ultimately, possibly to novel therapeutic approaches." (PMID 24475098, 2014). "Notably, BAG5 has been reported to act as a co-chaperone by regulating HSP70-mediated protein folding in Parkinson’s disease (PD) and HSPA8-mediated proteostasis in dilated cardiomyopathy." (PMID 38454159, 2024). "This suggests that BAG5 protein may play an important role in the progression of Parkinson’s disease." (PMID 35821856, 2022). "Interestingly, it has been reported that the interaction of BAG5 and DJ-1 protein may enhance apoptotic cell death in neurodegenerative disorders, including Parkinson’s disease." (PMID 35821856, 2022).
ovarian carcinoma (6 papers, 2013 to 2025). A malignant neoplasm originating from the surface ovarian epithelium. "Further, the authors found that knockdown of the BAG5 causes metabolic reprogramming and maintenance of cancer stem cells like feathers of the ovarian cancer cells." (PMID 35821856, 2022). "Here, we show that BAG5 overexpression correlates with increased Akt expression at the protein level in tumors of uterine and ovarian cancer patients." (PMID 38139359, 2023). "Additionally, it was demonstrated that suppression of BAG5 may cause the upregulation of the rictor-mTORC2 pathway which modulates cellular metabolism and cancer stem cell-like feathers of cisplatin-resistant ovarian cancer cells." (PMID 35821856, 2022). "Next, we analyzed whether a change in Akt protein expression was evident in tumors with BAG5 overexpression compared to all other tumors in breast, uterine, lung, and ovarian cancer types." (PMID 38139359, 2023). "Additionally, we identified some candidate genes linked to reproductive diseases, such as NRG3 and XRCC3 for ovarian cancer, and BAG5, CKB and XRCC3 for endometriosis." (PMID 33477586, 2021). "MiR-127-3p acts as a tumor growth suppressor by targeting KIF3, ITGA6, and BAG5 in SCC, osteosarcoma, and ovarian cancer." (PMID 33396321, 2020). "This agrees with finds that Bag5 gene expression is increased in rat livers upon exposure to epatotoxants and that it is induced in MCF7 breast cancer cells and ovarian cancer spheroids upon taxol treatment." (PMID 23448667, 2013).
prostate carcinoma (5 papers, 2013 to 2021). A carcinoma that arises from epithelial cells of the prostate gland. "Recent studies have shown that Bcl-2-associated athanogene 5 (Bag5) is over-expressed in prostate cancer and inhibits ER stress-induced apoptosis." (PMID 30662442, 2018). "In prostate cancer cells, Bag5 overexpression inhibits ER stress-induced apoptosis in the UPR by suppressing PERK-eIF2-ATF4 activity while enhancing the IRE1α–XBP1 axis." (PMID 34663798, 2021). "We have therefore shown that Bag5 is overexpressed in prostate cancer and plays a role in ER-stress induced apoptosis." (PMID 23448667, 2013). "Since other Bag family members are overexpressed in several types of cancers in addition to prostate cancer, such as breast, colon and pancreatic cancers, it is likely that increased Bag5 expression would be found in other type of tumors as well." (PMID 23448667, 2013). "Bag5 overexpression in 22Rv.1 prostate cancer cells inhibited ER-stress induced apoptosis in the unfolded protein response by suppressing PERK-eIF2-ATF4 activity while enhancing the IRE1-Xbp1 axis of this pathway." (PMID 23448667, 2013). "Bag5 mRNA and protein expression levels were investigated in prostate cancer patient samples using real-time PCR and immunoblot analyses." (PMID 23448667, 2013). "GST-pull down assay was therefore carried out with GST-fused Bag5 and lysates of 22Rv.1 prostate cancer cells." (PMID 23448667, 2013). "Functional studies of the role of Bag5 in prostate cancer cell lines was performed using overexpression and RNA interference analyses." (PMID 23448667, 2013). "In this communication we show that Bag5 is overexpressed in prostate cancer and exerts an anti-apoptotic function." (PMID 23448667, 2013). "This hypothesis is supported by our observation that up- or downregulation of Bag5 levels modifies the ability of prostate cancer cells to respond to stress." (PMID 23448667, 2013). "Furthermore, analysis of Bag5 expression was performed in an immunoblot assay on Gleason 9 prostate cancers and their corresponding benign surrounding area." (PMID 23448667, 2013). "In addition we showed for the first time at the RNA and protein levels that Bag5 is overexpressed in prostate cancer and that it plays a role as a pro-survival factor in UPR-induced apoptosis." (PMID 23448667, 2013). "In addition, BAG5 is elevated in prostate cancer and represses ER‐stress triggered apoptosis." (PMID 33481351, 2021). "To determine whether Bag5 plays a role in prostate cancer development, we first analyzed its expression in benign prostatic hyperplasia (BPH) and compared it with its expression in prostate cancer." (PMID 23448667, 2013). "The tumor-specific expression of Bag5 was not restricted to biopsies but could be reproduced in a cell culture model of prostate cancer progression where RWPE-1, WPE-NB14 and WPE-NB26 represent different stages of malignancy from benign to a more aggressive prostate tumor state." (PMID 23448667, 2013).
breast carcinoma (4 papers, 2013 to 2023). "We further analyzed the association of BAG5 expression levels with prognosis in the breast cancer patients by using the KM-plot database." (PMID 27807478, 2016). "Similar to BAG2, BAG5 is overexpressed in many human tumors (colorectal cancers, lung cancers, breast cancers and skin) with a positive correlation with poor prognosis of breast cancer patients." (PMID 30577483, 2018). "BAG5 is overexpressed in many types of human cancers, including breast cancer, skin cancer, lung cancer and colorectal cancers, compared with normal tissues as analyzed in four databases from Oncomine." (PMID 27807478, 2016).
Alzheimer disease (3 papers, 2016 to 2025). A progressive, neurodegenerative disease characterized by loss of function and death of nerve cells in several areas of the brain leading to loss of cognitive function such as memory and language. "Using human neuroblastoma cells (SH-SY5Y), Guo and co-workers reported that BAG5 expression is modulated in Alzheimer’s disease." (PMID 35821856, 2022). "Furthermore, the authors revealed that BAG5 expression at both transcriptional and translational levels is upregulated in the transgenic mice suffering from Alzheimer’s disease." (PMID 35821856, 2022).
colorectal cancer (2 papers, 2016 to 2020). A primary or metastatic malignant neoplasm that affects the colon or rectum.
hepatocellular carcinoma (2 papers, 2021 to 2025). A malignant tumor that arises from hepatocytes. "BAG5 functions as downstream of circ_0008305 to trigger hepatocellular carcinoma (HCC) progression." (PMID 40787462, 2025).
pancreatic cancer (2 papers, 2022 to 2025). "Besides, BAG5 is indicated to be a suppressor in pancreatic cancer." (PMID 35504036, 2022).
papillary thyroid cancer (2 papers, 2021 to 2022). "For example, BAG5 might involve in the invasion of papillary thyroid cancer cells." (PMID 35504036, 2022).
Arrhythmia (1 paper, 2024). Any cardiac rhythm other than the normal sinus rhythm. "Notably, we observe a heightened susceptibility to arrhythmias among female carriers in humans, as well as in heterozygous and homozygous Bag5 mutant male mice." (PMID 38796549, 2024). "Here, our study reveals a novel BAG5 mutation causing DCM by impairing the ER stress response, with observed sex-specific arrhythmia differences." (PMID 38796549, 2024). "Overall, of the three Bag5−/− males, one died suddenly, and the second one had arrhythmia." (PMID 38796549, 2024). "Of the three TN-treated Bag5+/− male mice, one (33%) had arrhythmias." (PMID 38796549, 2024). "Interestingly, only Bag5 KI male mice demonstrated arrhythmia, which was more pronounced in Bag5−/− than in Bag5+/−males." (PMID 38796549, 2024). "We found that cardiac arrhythmia is a sex-specific, found only in male KI mice, irrespective of monoallelic or biallelic BAG5 mutations." (PMID 38796549, 2024). "Of the three TN-treated Bag5−/− male mice, one (33%) had arrhythmias and another one died suddenly without obvious explanation." (PMID 38796549, 2024). "Furthermore, ECG showed that one Bag5−/− and one Bag5+/− males, but not females, experienced arrhythmia after TN injection which indicated by long electrical standstills (sinus pause)." (PMID 38796549, 2024). "None of the Bag5−/− and Bag5+/− female mice manifested arrhythmia." (PMID 38796549, 2024).
cardiomyopathy (1 paper, 2024). A disease of the heart muscle or myocardium proper. "Future studies that aim to broaden our understanding of proteotoxic stress beyond ER stress will allow us to gain a more holistic view of the pathobiology underlying BAG5-related cardiomyopathy." (PMID 38796549, 2024).
cerebrovascular disorder (1 paper, 2022). A disorder resulting from inadequate blood flow in the vessels that supply the brain. "Since BAG5 protein expresses in the heart and brain, it has become a novel target that can be exploited for the development of treatment strategies for curing cardiovascular and cerebrovascular disorders." (PMID 35821856, 2022).
cervical cancer (1 paper, 2025). A primary or metastatic malignant neoplasm involving the cervix. "Notably, BAG2 expression was significantly reduced in cervical cancer, while no significant changes were observed in other BAG family members (BAG1, BAG3, BAG4, BAG5, and BAG6), suggesting a unique role for BAG2 in cervical cancer." (PMID 40364789, 2025).
cyst (1 paper, 2013). A sac-like closed membranous structure that may be empty or contain fluid or amorphous material. "More recently, tissue cyst production, marked by positive staining with an antibody directed against the Toxoplasma bradyzoite antigen BAG5, has also been demonstrated in an experimentally infected carnivorous marsupial, the fat-tailed dunnart Sminthopsis crassicaudata." (PMID 27335863, 2013).
dementia with Lewy bodies (1 paper, 2011). "We performed immunohistochemistry for α-syn, CHIP, and BAG5 on substantia nigra pars compacta samples from two patients with a neuropathological diagnosis of dementia with Lewy bodies (DLB), a neurodegenerative disease with histopathology similar to PD." (PMID 21358815, 2011).
depression (1 paper, 2020). "Three replicated loci were previously reported (ITIH3, FHIT, BAG5), but the other seven (ZNF804A, MIR3143, PSORS1C2, STK19, SPATA31D1, RTN1, TCF4) were novel for depression." (PMID 30626913, 2020).
dilatation (1 paper, 2022). "Furthermore, this study shows that mouse models with the BAG5 gene mutation (Arg197Ter) have ventricular dilatation and dysregulation of calcium handling with arrhythmogenicity, suggesting that BAG5 is important for cardiac function." (PMID 35821856, 2022).
dilated cardiomyopathy (1 paper, 2024). Cardiomyopathy which is characterized by dilation and contractile dysfunction of the left and right ventricles. "Pathogenic BAG5 variants recently linked to dilated cardiomyopathy (DCM) prompt further investigation into phenotypic, mutational, and pathomechanistic aspects." (PMID 38796549, 2024).
endometrial cancer (1 paper, 2025). Primary or metastatic malignant neoplasm involving the endometrium (mucous membrane that lines the endometrial cavity). "Gene set variation analysis (GSVA) revealed that BAG5+ cells were enriched in multiple oncogenic pathways, including those involved in colorectal, pancreatic, and endometrial cancers, which suggests that BAG5 may converge on evolutionarily conserved oncogenic programs." (PMID 40787462, 2025).
endothelial dysfunction (1 paper, 2022). In vascular diseases, endothelial dysfunction is a systemic pathological state of the endothelium (the inner lining of blood vessels) and can be broadly defined as an imbalance between vasodilating and vasoconstricting substances produced by (or acting on) the endothelium. "The study unraveled that BAG5 overexpression could overcome catecholamine-dependent endothelial dysfunction and improve cell survival via decreasing oxidative stress and improving endothelial cell survival." (PMID 35821856, 2022). "Similarly, another recent study reported that BAG5 acts as an ER stress regulator and its expression contributes to maintaining endothelial cell viability and protects cells from endothelial dysfunction." (PMID 35821856, 2022).
glaucoma (1 paper, 2020). Increased pressure in the eyeball due to obstruction of the outflow of aqueous humor. "It is important to note that some of our positional candidates—Eif5, Bag5, Klc1, and Ppp1r13b—have been previously demonstrated to play a role in glaucoma and/or RGC health." (PMID 32174956, 2020).
ischemia (1 paper, 2019). A hypoperfusion of the BLOOD through an organ or tissue caused by a PATHOLOGIC CONSTRICTION or obstruction of its BLOOD VESSELS, or an absence of BLOOD CIRCULATION. "have found that BAG5 also attenuates mitochondrial Parkin localization in the context of mitochondrial Hexokinase-II dissociation induced-mitophagy, a pathway that may be important in conferring cardioprotection against ischemia." (PMID 31787745, 2019).
lung adenocarcinoma (1 paper, 2010). A carcinoma that arises from the lung and is characterized by the presence of malignant glandular epithelial cells. "BAG-1, BAG-2, BAG-5 might be the potential protective factors while BAG-4 is possible risk factor of lung adenocarcinoma." (PMID 20959066, 2010).
male infertility (1 paper, 2024). The inability of the male to effect fertilization of an ovum after a specified period of unprotected intercourse. "Here, we first report that loss of BAG5 in mice results in acephalic spermatozoa syndrome and male infertility, accompanied by disorganization of the HTCA." (PMID 38454159, 2024). "BAG5-deficient male mice show abnormal assembly of HTCA, leading to ASS and male infertility, phenocopying SPATA6-deficient mice." (PMID 38454159, 2024).